MMP11 (matrix metallopeptidase 11)
Diseases named in the same sentence as MMP11 in open-access papers (continued):
Sharing a sentence is not in itself a finding about the gene and the disease.
tumor (continued). "In addition, it is interesting our finding indicating that if there is a high CD68/(CD3+CD20) ratio at the invasive front, most of MICs with a positive MMP-11 or TIMP-2 phenotype at the tumor center are macrophages (respectively)." (PMID 23300781, 2012). "Also, we found that high CD68 count and CD68/(CD3+CD20) ratio were associated with both MMP-11 and TIMP-2 expressions by MICs at the tumor center." (PMID 23300781, 2012). "The observation that miR-98 expression inhibited tumor invasion could be explained by the down-regulation of MMP11." (PMID 23211491, 2012). "In addition, it is remarkable our finding indicating that if there is a high CD68/(CD3+CD20) ratio at the invasive front, most of MICs with a positive MMP-11 or TIMP-2 phenotype at the tumor center are macrophages." (PMID 23300781, 2012). "In an investigation of gene expression during tumor progression in the breast, it was found that extensive changes in gene expression occur in tumor-associated stroma, including increased expression of MMP2, MMP11, and MMP14 during the transition from a preinvasive to invasive phenotype." (PMID 21647291, 2011). "Furthermore, investigating the interaction of MMP11 with other components of the tumor microenvironment may identify novel therapeutic targets for preventing malignant transformation and recurrence." (PMID 40843631, 2026). "Clinically, elevated MMP-11 levels in patients with EnOC may indicate increased activity of extracellular matrix remodeling processes and tumor progression, consistent with the role of this metalloproteinase in regulating the tumor microenvironment and facilitating tumor invasion." (PMID 41007705, 2025). "However, the significance of MMP11 in the tumor microenvironment, immune/stromal cells, and its mechanism in CRC remain unclear." (PMID 39239548, 2024). "Consequently, we hypothesized that MMP11 enabled tumor cell immune escape in CRC by modifying the immune microenvironment." (PMID 39239548, 2024). "However, whereas most MMPs are secreted as proenzymes that need extracellular activation, MMP-11 is processed intracellularly and secreted as an active enzyme, suggesting that MMP-11 may have a unique role in tumor development and progression." (PMID 37108185, 2023). "Importantly, specific upregulation of MMP11 in CAS of metastatic tumours was validated by qPCR." (PMID 37391533, 2023). "Compared to other MMPs, MMP-11 has unique features that may contribute to tumor development and invasion; it is constitutively active and strongly regulates the serine protease inhibitor α1-antitrypsin, insulin-like growth factor binding protein-1 (IGFBP-1), and collagen IV." (PMID 36139587, 2022). "MMP11 is a potent physiologic negative regulator of adipogenesis, and its expression in adipocytes was shown to be induced by tumor cells, in turn leading to the accumulation of non-malignant peritumoral fibroblast-like cells, promoting cancer cell survival and tumor progression." (PMID 32120856, 2020). "Thus, MMP11 plays the central role during tumor desmoplasia." (PMID 32120856, 2020). "These adipocytes located near the tumor are called “cancer-associated adipocytes” (CAA) and are characterized by a loss of lipid content, a decrease in late marker expression of adipogenesis, and an overexpression of inflammation markers (IL-6, IL-1β) and proteases (MMP-11, PAI-1)." (PMID 31756890, 2019). "The expression of MMP11 in GC tumor tissues was also detected, and we found that MMP11 was significantly decreased in miR-139-exosome group compared with NC-exosome group; suggesting MMP11 was involved in the inhibitory effects of exosomal miR-139 on tumor growth and metastasis of GC cells." (PMID 31595150, 2019). "Cancer-associated adipocytes have been associated with enhanced production of matrix metalloproteinase-11 (MMP-11) and pro-inflammatory cytokines (IL-1β and IL-6), as well as increased degradation of lipids, to provide additional energy to malignant cells at the tumour front." (PMID 30261606, 2018).
tumor (continued). "Hence, due to the fact that MMP11 is expressed very early in tumor invasion processes, MMP11 could be one essential factor that initiates this metabolic reprogramming in CAAs and CAFs." (PMID 27126782, 2016). "Both CD147 and MMP-11 might act as tumor promoters during the progression of CRC patients." (PMID 26507719, 2015). "MMP-11 expression by mononuclear inflammatory cells (MICs) coupled with the expression of pro-inflammatory proteins support tumor escape and invasion, hence promoting metastasis, so they claim that the expression of MMP-11 may constitute a useful biological marker for pro-metastatic MICs." (PMID 26507719, 2015). "In this series, the expression of MMP-1 both in tumor and in peritumoral fibroblasts, and of MMP-11 in neoplastic cells, could explain the phenomenon of break-down of cell elements related to the blood vessel wall, such as type IV collagen, laminin and fibronectin." (PMID 18954439, 2008). "Similarly to other studies, our data showed that MMP-11 (Stromalysin-3) was preferentially expressed by peritumoural stromal cells and that high levels of MMP-11 were associated with tumour progression and poor prognosis." (PMID 17848954, 2007). "MMP7 and MMP11 were significantly upregulated in primary SKCM but showed reduced expression in metastatic samples, suggesting their involvement in early tumor invasion and progression." (PMID 40604111, 2025). "Myofibroblast-like CAFs (myoCAFs) expressing matrix metalloproteinase-11 (MMP11) and tenascin C (TNC) drive matrix sclerosis and tumor dissemination." (PMID 41479912, 2025). "MMP11 is highly expressed in LUAD and promotes tumor development, invasion, and ECM remodeling through autocrine signaling." (PMID 40826767, 2025). "A total of 22 MMPs were found to be abnormally expressed in UCEC tumor tissues, with MMP11 and MMP17 significantly enriched in the tumor’s ECM." (PMID 41228294, 2025). "We identified MMP11 and MYL9 as potential biomarkers for advanced disease stages and underscore the context-dependent role of DEFA family genes in tumor progression—supported by stage-specific pathway analyses and cross-species validation." (PMID 41009818, 2025). "MMP7 and MMP11 showed moderate cytoplasmic staining, while MMP14 exhibited stronger and more diffuse staining, suggesting its prominent role in tumor invasion and extracellular matrix remodeling." (PMID 40604111, 2025). "In summary, we identified pro-tumorigenic CAF_MMP11 in the CRC tumor microenvironment, which are more prevalent in males and likely promote tumor progression by modulating cell-cell interactions and ECM remodeling, indicating a sex-disparate distribution." (PMID 40520886, 2025). "The paired sample comparison graph demonstrated that the expression levels of ILF3, MMP9, MMP10, MMP11, and MMP26 in PCa tumor tissue were elevated than adjacent non-tumor tissues (P < 0.05)." (PMID 40607407, 2025). "PPI analysis revealed COL10A1, POSTN, SPP1, MMP11, and GREM1 as key hub genes in extracellular matrix (ECM) remodeling and tumor progression." (PMID 40826767, 2025). "Isoform structure analysis using GEPIA2 revealed functional diversity in MMP7, MMP11 and MMP14, highlighting their roles in ECM degradation and tumor progression." (PMID 40604111, 2025). "Compared with normal tissues, the top three downregulated genes in the tumor tissues were FABP4, SAA1, and SFRP1, while the top three upregulated genes were COMP, COL10A1, and MMP11." (PMID 40936892, 2025). "Pseudo-time trajectory analysis revealed increased expression of MMP11 and MYL9 in later stages of tumor progression." (PMID 41009818, 2025). "GO pathway enrichment analysis confirmed CAF_MMP11's role in ECM-related pathways, highlighting its contribution to tumor progression and metastasis." (PMID 40520886, 2025). "Fibroblasts in the presence of UPP1-overexpressing tumor cells displayed a higher CAF score and increased expression of CAF markers such as FAP and MMP11." (PMID 38331898, 2024).
tumor (continued). "Parietal peritoneal thickening showed the overexpression of LUM, MMP11, and DUSP1 in the tumor region, MMP11 and CTSK in the stromal region, and MMP11 and CTSK in the immune region (adjusted p-values ≤ 0.002)." (PMID 39135097, 2024). "This analysis prompted a focus on specific MMPs more distinctly expressed in CC2, such as MMP2, MMP9, MMP11, MMP14, and MMP25, suggesting their potential role in tumor invasion and their clinical relevance as potential therapeutic targets." (PMID 38893149, 2024). "Let-7c acts as a tumor suppressor for CRC development and metastasis by disrupting mRNAs of MMP11 and PBX351." (PMID 38632250, 2024). "Analysis of the DEGs in TCGA tumours revealed that the miR-18a/low tumours expressed high levels of EMT master regulators-ZEB1 and ZEB2 and Matrix metalloproteinases, MMP2, MMP3, MMP10, MMP11, MMP13 and MMP17 (p < 0.05)." (PMID 38786043, 2024). "This study did not primarily focus on tumor heterogeneity, but it is important to recognize that a low MMP-11 immunohistochemical score can be associated with localized MMP-11 expression, which might indicate local progression, through MMP-11 function on substrates like IGFBP1 and Collagen VI." (PMID 38438841, 2024). "Immunomorphometry analyses revealed that FOXQ1-, MMP11- and THBS2-positive cells were present at significantly higher numbers in the CC tumor region than in normal colon epithelium (P < 0.0001)." (PMID 38156105, 2023). "The findings demonstrated that high levels of MMP11 in patients with EGFR-mutant LUAD are associated with a poor immune response and may control the tumor immune microenvironment, which fosters an immunosuppressive environment and aids in the immune escape of tumor cells." (PMID 36756152, 2023). "The interaction between adipocytes and PC cells also enhances the expression of MMP-11 in PC cells, which has been reported to inhibit apoptosis and is capable of degrading ECM components for tumor invasion or migration." (PMID 37554282, 2023). "We further identified the top 100 specifically expressed genes in the tumor boundary of the three CRC ST samples which overlapped significantly, and included SPP1, MMP11, and COL1A1." (PMID 36806082, 2023). "The most important finding in this study is that the expression levels of the fibroblast biomarkers FOXQ1, MMP11 and THBS2 are significantly elevated in both primary tumor tissue and H&E(+)LNs of CC patients." (PMID 38156105, 2023). "Potential correlation between levels of the fibroblast biomarkers FOXQ1, MMP11 and THBS2 in primary tumor tissue was investigated." (PMID 38156105, 2023). "The results showed that the expression of FGA, OTC, and CTH in the tumor tissues of patients with CCA is significantly lower than that in normal tissues, but that the expression of MMP11 is significantly higher than that in normal tissues." (PMID 36300097, 2022). "In BCC's stroma and the peritumoral area, CAFs can secrete an array of MMPs (e.g., MMP-1, MMP-2, MMP-3, MMP-9, MMP-11, MMP-13, MMP-14, MMP-19), all of them promoting ECM remodeling and favoring tumor escape from the anti-tumoral action of the immune cells." (PMID 35572966, 2022). "The differential analysis also confirmed the high expression of CD74, HLA-DRA, C7, CCL12, and CCR3 in CAFs from P-LN but lower expression of VIM, APOD, MMP11, TAGLN, and CDKN2A compared with that in the primary tumor." (PMID 36569924, 2022). "The special ability of MMP-11, which is different from other MMP members, suggests that it plays a distinct role in tumor development and progression." (PMID 34038440, 2021). "MMP11, MMP14, MMP16, MMP17, MMP19, and MMP23b were positively correlated with the tumor stage, that is, the mRNA levels of MMPs in patients with higher tumor stage were always high." (PMID 34804973, 2021).
tumor (continued). "We also evaluated the protein level of MMPs in our patients and measured the expression level of MMP1–MMP3, MMP7–MMP9, MMP11, MMP12, MMP14, MMP17, MMP19, and MMP28 in their tumor tissue and adjacent normal tissue by Western blot." (PMID 34804973, 2021). "“Basal-like” subtype presents KRASG12D mutation, while “activated” stroma subtype expresses SPARC, WNT family members WNT2 and WNT5A, gelatinase B (MMP9), stromelysin 3 (MMP11), and FAP that contribute to tumor development." (PMID 33477288, 2021). "In our study, we studied the impact of MMP11 on ER stress and the UPRER in tumor samples from 6-week-old PyMTTg; MMP11Tg and 10-week-old PyMTTg; MMP11KO mice and their respective controls." (PMID 32825455, 2020). "Expression of MMP11 and COL10A1 increased significantly from pDCIS to DCIS of DCIS/IBC mixed tumours." (PMID 30236106, 2018). "Based on these data collected in vitro, we measured the expression level of MMP11, Zbtb7a, SIRT7 and c-Raf in tumor biopsies, focusing on those patients showing a downregulation of miR-125a of at least 2-fold." (PMID 28445974, 2017). "MMPs were reported to induce tumor progression in HCC including MMP-1, MMP-2, MMP-3, MMP-7, MMP-9, MMP-11 and MMP-13." (PMID 26882566, 2016). "Since MMP-14 is produced by HT-1080 cancer cells, whereas MMP-11 is secreted by HFL1 stromal cells, our findings support the emerging importance of tumor-stroma interaction/cross-talk." (PMID 25081520, 2014). "Among the studied genes, the overexpression of the following metalloproteinases in the tumor tissue can be correlated to at least one clinicopathological variable: MMP-1, MMP-2, MMP-9, MMP-11, and MMP-16." (PMID 24737953, 2014). "To date, a number of genes have been identified that modulate lymphatic tumor metastasis when they are highly expressed in certain tumor cells, such as Ezrin, AF1QN, MMP-11, or Annexin A7." (PMID 24188284, 2013). "Our findings define a regulatory role of miR-98 in tumor angiogenesis and invasion through repressed ALK4 and MMP11 expression." (PMID 23211491, 2012). "In this study, we report that miR-98 interferes with tumor invasion and angiogenesis by repressing ALK4 and MMP11 expression." (PMID 23211491, 2012). "In summary, we have demonstrated that miR-98 functions as a tumor suppressor by inhibiting cell survival, cell proliferation, tumor growth, tumor invasion, and blood vessel expansion, primarily by targeting ALK4 and MMP11." (PMID 23211491, 2012). "We have previously reported that mRNAs for several MMPs, including Mmp2, Mmp3, Mmp11 and Mmp14 are expressed in the MMTV-PyMT tumor stroma." (PMID 18698413, 2008). "H&E staining at higher magnification in an adjacent tissue slice revealed that the expression of CTS, MMP11 and MMP12 was usually confined to the cytoplasm of a subset of epithelial tumor cells with morphological features of squamous differentiation." (PMID 15989693, 2005). "Using quantitative RT–PCR, overexpression of MMP1, MMP3, MMP7, MMP11, MMP12 and MMP13 in desmoid tumours was demonstrated." (PMID 15054469, 2004). "This suggests that MMP11 and MYL9 may drive CRC progression by contributing to therapy resistance—possibly through reduced tumor immunogenicity or the establishment of an immunosuppressive microenvironment." (PMID 41009818, 2025). "Although we demonstrated that DEFA3 inhibits proliferation and migration of CT26 cells in vitro, and linked MMP11/MYL9 expression to advanced CRC in human datasets, we did not test the functional impact of these genes in living tumor models." (PMID 41009818, 2025). "CAF_MMP11 was more prevalent in male CRC, suggesting a link to sex-specific tumor traits." (PMID 40520886, 2025). "Moreover, in tumor tissues from CRC patients, the expression levels of MMP11 and MLY9 showed a positive correlation." (PMID 41009818, 2025).
tumor (continued). "Immunofluorescence (IF) staining of tumor and adjacent normal tissue sections, using COL1A1 as a pan‐fibroblast marker and MMP11 as a specific marker, confirmed the predominant presence of MMP11+ mCAFs within the TME, supporting their potential functional relevance." (PMID 40552583, 2025). "Cluster C0, for instance, expressed high levels of matrix metalloproteinases (MMP13, MMP11) and alpha‐smooth muscle actin (ACTA2), a well‐known myofibroblast marker, signifying the presence of myofibroblasts known to promote tumour progression and angiogenesis." (PMID 38445456, 2024). "Specific MMPs, including MMP2, MMP9, MMP11, MMP14, MMP15, MMP25, and MMP28, were increased in this region, indicating their distinct roles in the tumor microenvironment and confirming the importance of understanding the effects of cysteamine on specific MMPs in GBM cancer models." (PMID 38893149, 2024). "In contrast, the high level of expression of MMP11 protein in CC tumor cells is not, or only partly, explained by ectopic expression since the level in normal colon epithelium was as high as 12%." (PMID 38156105, 2023). "The expression levels of PD-L1 in tumor cells were higher in the MMP11-positive expression group than in the MMP11-negative expression group." (PMID 36756152, 2023). "In the clinical samples, the infiltration levels of T cell CD8+ and NK cells in the tumor parenchyma of EGFR-mutant LUAD was lower in the MMP11-positive than in the MMP11-negative group." (PMID 36756152, 2023). "Immuno-morphometry revealed that 30–40% of the tumor cells expressed FOXQ1, MMP11, and THBS2." (PMID 38156105, 2023). "Conversely, 26 genes, including mediators of epithelial–mesenchymal transition (i.e., COL6A1/A2, COL16A1, MFAP5, MMP11), were co-expressed in tumor tissue but not in NAU." (PMID 35626146, 2022). "According to the expression pattern analysis, all the MMPs upregulated in CRC showed lower promoter methylation, except MMP11, while all the MMPs downregulated in CRC showed higher promoter methylation in tumor samples compared with normal samples, except for MMP15 and MMP27." (PMID 34830271, 2021). "To explore the anti-tumor effect of ProIFN, we first determined the expression levels of tumor-enriched enzymes such as MMP-2, MMP-9, MMP-11, MMP-14, fibroblast activation protein alpha (FAP), and urokinase plasminogen activator (uPA) in a variety of tumor lines." (PMID 34620867, 2021). "In addition, we found that the combination of tumor budding grade with MMP/TIMP expression by stromal cells, and especially with MMP-11 expression by mononuclear inflammatory cells, significantly improved the prognostic evaluation." (PMID 33669393, 2021). "The protein levels of MMP11 in our 12 pair samples were upregulated in tumor tissue for patients 2, 3, 6, 9, and 10 but not for other patients." (PMID 34804973, 2021). "To sum up, we speculate that MMP8, MMP11, TFDP3, F2, and CNTN1 can promote the progression of GAC while MYB could be a tumor suppressor in GAC." (PMID 32309437, 2020). "In this study, we compare tumor growth in GOF and LOF for MMP11 expression." (PMID 32825455, 2020). "Intriguingly, in many solid tumors, MMPs are produced by tumor stromal cells, rather than by tumor cells, including tumor-associated interstitial collagenase (MMP-1), stromelysin-1 (MMP-3), stromelysin-3 (MMP-11), and gelatinase A (MMP-2)." (PMID 32948029, 2020). "These biomarkers include ADAM17, MMP2, MMP9, and MMP11, survivin and CK19, vimentin, CXCR4, ING5, and Stanniocalcin2; in all of these examples, these molecules are overexpressed in tumoral GC tissues." (PMID 31249523, 2019). "Hence we validated gene expression of MMP1, MMP3, MMP11, MMP13, MMP14, ADAMTS1 and ADAMTS5 genes belonging to metallopeptidase activity, using qPCR in 67 tumours." (PMID 31292488, 2019).